USP37 (ubiquitin specific peptidase 37)
Description:
Deubiquitinase that plays a role in different processes including cell cycle regulation, DNA replication or DNA damage response. Antagonizes the anaphase-promoting complex (APC/C) during G1/S transition by mediating deubiquitination of cyclin-A (CCNA1 and CCNA2), thereby promoting S phase entry. Specifically mediates deubiquitination of 'Lys-11'-linked polyubiquitin chains, a specific ubiquitin-linkage type mediated by the APC/C complex. Phosphorylation at Ser-628 during G1/S phase maximizes the deubiquitinase activity, leading to prevent degradation of cyclin-A (CCNA1 and CCNA2). Plays an important role in the regulation of DNA replication by stabilizing the licensing factor CDT1. Also plays an essential role beyond S-phase entry to promote the efficiency and fidelity of replication by deubiquitinating checkpoint kinase 1/CHK1, promoting its stability. Sustains the DNA damage response (DDR) by deubiquitinating and stabilizing the ATP-dependent DNA helicase BLM. Mechanistically, DNA double-strand breaks (DSB) promotes ATM-mediated phosphorylation of USP37 and enhances the binding between USP37 and BLM. Promotes cell migration by deubiquitinating and stabilizing the epithelial-mesenchymal transition (EMT)-inducing transcription factor SNAI. Plays a role in the regulation of mitotic spindle assembly and mitotic progression by associating with chromatin-associated WAPL and stabilizing it through deubiquitination.
Synonyms: KIAA1594
Tractability: PROTAC: UniProt records ubiquitination sites on it; ubiquitination databases record sites on it.
Gene: Protein-coding gene on chromosome 2 (218,450,251 to 218,568,768, reverse strand). Ensembl gene ENSG00000135913.
Subcellular location: Nucleus; Chromosome
Subcellular location (Human Protein Atlas): Nucleoli; Nucleoplasm
Pathways (Reactome):
Metabolism of proteins: Ub-specific processing proteases
Gene Ontology:
Molecular function: cysteine-type deubiquitinase activity; cysteine-type endopeptidase activity; protein binding; protein kinase binding
Biological process: G1/S transition of mitotic cell cycle; protein deubiquitination; protein K11-linked deubiquitination; protein K48-linked deubiquitination; regulation of DNA replication
Cellular component: chromosome; nucleus; nucleoplasm
Genetic constraint (gnomAD): Loss-of-function variants: 21 observed, 107.58 expected, observed/expected ratio (o/e) 0.2, 90% interval 0.14 to 0.28. The upper end of that interval is the gene's LOEUF score, 0.28, which puts it in group 1 of 6, group 1 being the genes least tolerant of losing a copy. Missense variants: 823 observed, 1,101.2 expected, observed/expected ratio (o/e) 0.75, 90% interval 0.7 to 0.79. Synonymous variants: 342 observed, 375.02 expected, observed/expected ratio (o/e) 0.91, 90% interval 0.83 to 1.
Homologues: Orthologues: chimpanzee USP37 (99% identical), dog USP37 (96% identical), rabbit USP37 (94% identical), pig USP37 (93% identical), macaque USP37 (92% identical), mouse Usp37 (91% identical), guinea pig USP37 (86% identical), rat Usp37 (86% identical), tropical clawed frog usp37 (66% identical), zebrafish usp37 (57% identical). Paralogues in human: USP29 (43% identical), USP26 (41% identical), USP32 (16% identical), USP6 (13% identical), USP8 (13% identical), USP24 (13% identical), USP4 (13% identical), USP19 (13% identical), USP49 (12% identical), USP35 (12% identical), USP33 (12% identical), USP44 (12% identical), and 59 more.
Diseases named in the same sentence as USP37 in open-access papers:
USP37 is named in the same sentence as 37 diseases in open-access papers, as found by Europe PMC text mining. Sharing a sentence is not in itself a finding about the gene and the disease. The quoted sentences say what the papers report.
breast carcinoma (15 papers, 2018 to 2025). "Several studies have indicated that elevated expression of USP37 in various tumors is closely associated with patient prognosis, including colorectal cancer renal cancer, breast cancer, and gastric cancer." (PMID 40926837, 2025). "It will be interesting to further investigate the molecular mechanisms underlying the overexpression of the USP37–BLM axis in breast cancer." (PMID 34606619, 2021). "More recently, in a bioinformatic analysis of breast cancer (BC), The Cancer Genome Atlas (TCGA) database revealed upregulation of USP37 that is associated with increased mortality." (PMID 34758854, 2021). "It was verified by the observation that USP37 downregulation elevated the inhibitory effects of adriamycin on breast cancer cells, suppressed cell proliferation caused by cell cycle arrest in G1/S transition, as well as induced apoptosis." (PMID 33390801, 2021). "GSEA analysis showed that USP37 expression was positively associated with cell growth and metastasis while negatively related to cell apoptosis in the TCGA breast cancer samples." (PMID 30482232, 2018). "Ubiquitin-specific peptidase 37 (USP37) has been recently identified as a modulator in regulating the stemness of breast cancer cells, but its underlying mechanism remains unclear." (PMID 33390801, 2021). "While researchers have demonstrated that CD44 and ALDH1 are critical biomarkers to identify BCSCs from breast cancer populations, our data suggested that the USP37 gene was significantly associated with CSC properties, such as self-renewal, treatment resistance and EMT phenotype as well." (PMID 30482232, 2018). "Previous studies have also highlighted USP37’s high expression in breast cancer stem cells, correlating with a poor prognosis in breast cancer patients." (PMID 40926837, 2025). "For instance, USP37 exhibits high expression levels in breast CSCs and is correlated with unfavorable prognosis among patients diagnosed with breast cancer." (PMID 40034124, 2025). "The TCGA-BRCA cohort analysis emphasizes a potential interplay of metabolic genes like NDUFS1, TRPM4, ARMCX5, SLCO6A1, and epigenetic axis genes like SETDB1 and USP37 in the oncogenesis and prognosis of breast carcinomas." (PMID 41503337, 2025). "USP37 was shown to be highly expressed in the cytoplasm of breast cancer patients and is an independent poor prognostic parameter for overall survival, recurrence-free survival, and metastasis-free survival." (PMID 37118828, 2023). "In cisplatin-resistant breast cancer cells, elevated expression of ubiquitin-specific peptidase 37 (USP37) upregulated the expression of purmorphamine (PM)." (PMID 36313710, 2022). "Taken together, these results suggest that USP37 regulates cellular response to cisplatin or IR in breast cancer cells in a BLM-dependent manner." (PMID 34606619, 2021). "It was suggested that knockdown of USP37 expression combined with adriamycin treatment was closely correlated with adriamycin sensitivity of breast cancer." (PMID 33390801, 2021). "Through knockdown of USP37 expression in breast cancer MCF-7 cells and MCF-7/ADR cells with a lentivirus vector system, we demonstrated that USP37 downregulation can evidently inhibit cellular proliferation of breast cancer cells." (PMID 33390801, 2021). "We found that USP37 immunoreactivity was the lowest in MCF-10A cells among the three types of breast cancer cells studied in this paper." (PMID 33390801, 2021). "In this study, we found USP37 is over-expressed in adriamycin-resistant breast cancer cells and the increase showed a dose-dependent manner with the exposure to adriamycin." (PMID 33390801, 2021). "The efficiency of USP37 knockdown in breast cancer cells was confirmed by western blotting and RT-qPCR assays." (PMID 33390801, 2021). "To further determine the clinical relevance between USP37–BLM axis and breast cancer, we examined the expression of USP37 and BLM in breast cancer samples." (PMID 34606619, 2021).
breast carcinoma (continued). "For example, USP37 is overexpressed in breast cancer and promotes cell migration, invasion and EMT by regulating hedgehog signaling pathway." (PMID 34405018, 2021). "Some studies have demonstrated that USP37 is exceptionally overexpressed in some malignant tumor tissues, especially in lung cancer and breast cancer." (PMID 33390801, 2021). "Conventionally, USP37 gene was regarded as a stem marker and its overexpression maintained the stemness of breast cancer." (PMID 33390801, 2021). "Recent work highlights the role of USP37 in stimulating the epithelial-mesenchymal transition and metastasis in lung and breast cancer by stabilizing SNAI1 and stimulating the sonic hedgehog pathway, respectively." (PMID 34758854, 2021). "Collectively, these data suggest that overexpression of USP37 correlates with up-regulation of BLM in human breast cancer tissues." (PMID 34606619, 2021). "Up to this point, we determined that USP37 overexpressed in breast cancer cell lines and overexpression of USP37 lead breast cancer cells to be more resistant to chemo or radiotherapy." (PMID 34606619, 2021). "Overall these data indicate the relevance of USP37 in the regulation of breast cancer progression via the activation of the HH pathway." (PMID 32531973, 2020). "In this study, we have demonstrated overexpression of USP37 in Luminal B subtype breast cancer was a predictor of poor outcomes in breast cancer." (PMID 30482232, 2018). "In order to elucidate the function of USP37 in the migration and invasion of breast cancer cells, we conducted wound healing and Transwell assays to detect the role of USP37 in cell migration and invasion." (PMID 30482232, 2018). "The USP37 expression in breast cancer tissues and breast cancer cell lines were detected by immunohistochemistry and western blotting." (PMID 30482232, 2018). "To investigate the effects of USP37 on breast cancer progression, we used siRNA oligonucleotides to knockdown endogenous USP37 in MCF-7 and MDA-MB-231 cells." (PMID 30482232, 2018). "Taken together, these results indicated that elevated expression of USP37 was enriched in breast CSCs and was a novel feature of breast cancer stem cell-like subpopulation." (PMID 30482232, 2018). "Gene set enrichment analysis (GSEA) was utilized to evaluate potential mechanism of USP37 in breast cancer." (PMID 30482232, 2018). "To validate the expression levels of the USP37 gene in breast cancer stem cells, we isolated CD24−/CD44+ cell populations from MCF-7 cell lines by magnetic activated cell sorting (MACS)." (PMID 30482232, 2018). "Bioinformatics analysis demonstrated that USP37 gene was elevated in breast cancer tissues and its overexpression was strongly correlated with the increased mortality rate." (PMID 30482232, 2018). "USP37 is required for the regulation of breast cancer progression, as well as a critical target for clinical treatment of breast cancer." (PMID 30482232, 2018). "In this study, we found that USP37 expression was upregulated in breast cancer tissues compared with surrounding tissues and its overexpression was significantly correlated with increased rates of mortality." (PMID 30482232, 2018). "For investigation of the correlation between USP37 gene and the breast cancer heterogeneity, we also tested USP37 expression in the four cell subtypes using PAM50 gene expression profiling." (PMID 30482232, 2018). "USP37 mRNA expression levels significantly decreased with two different siRNAs treated breast cancer cells compared to levels in the control group cells." (PMID 30482232, 2018). "In vitro and in vivo assays were performed to examine the biological functions of USP37 in breast cancer cells." (PMID 30482232, 2018). "In summary, we suggest that USP37 gene expression confers the stemness and potentially acts as a critical marker of CSCs in breast cancer." (PMID 30482232, 2018).
breast carcinoma (continued). "In order to investigate the role of USP37 in tumorigenesis, we examined the breast cancer database of The Cancer Genome Atlas (TCGA) to evaluate the differential expression of USP37." (PMID 30482232, 2018). "In conclusion, our research demonstrated that USP37 was highly expressed in breast CSCs and was correlated with poor prognosis in breast cancer patients." (PMID 30482232, 2018). "Supporting our results, previous clinicopathological analysis has demonstrated that overexpressed USP37 is considered to be a poor prognosis in breast cancer." (PMID 30482232, 2018). "Collectively, these data suggest that USP37 is abnormally overexpressed in human breast cancer patients and cell lines." (PMID 30482232, 2018). "We next estimated the effect of USP37 as an oncogenic biomarker for overall survival of patients diagnosed with breast cancer." (PMID 30482232, 2018). "Recently, clinicopathological analysis confirmed that USP37 was a poor prognostic factor in breast cancer." (PMID 30482232, 2018). "The distribution of USP37 expression in breast cancer and the correlation between USP37 expression and the overall survival rate were detected by The Cancer Genome Atlas (TCGA) database." (PMID 30482232, 2018). "For example, USP37 enhances breast cancer progression by stabilizing estrogen receptor alpha (ERα)." (PMID 40926837, 2025). "For instance, USP37 promotes breast cancer progression by stabilizing ERα through deubiquitination." (PMID 40926837, 2025). "In addition, GEO database showed that high expression of USP37 is related to poor survival in breast cancers." (PMID 34606619, 2021). "Taken together, USP37 upregulation was involved in adriamycin resistance of breast cancer cells, and USP37 might be a prospective therapeutic biological marker for monitoring and overcoming breast cancer adriamycin resistance." (PMID 33390801, 2021). "It has been indicated that USP37 may be a new molecular marker in the gene-targeted therapy of breast cancer." (PMID 33390801, 2021). "Moreover, a positive correlation between BLM and USP37 protein levels was observed in the breast carcinomas supporting a role for the activity of the USP37–BLM axis in human breast cancer cells." (PMID 34606619, 2021). "Finally, we demonstrated that high level of USP37 mediated cisplatin or IR resistance in breast cancer in a BLM-dependent manner and clarified the role of USP37 as a potential therapeutic target in breast cancer." (PMID 34606619, 2021). "The present study focused on the role of USP37 in adriamycin resistance of breast cancer." (PMID 33390801, 2021). "Up-regulation of USP37 was detected in 84.5% (93 of 110) of breast cancer tissues, while 82.5% (66 of 80) of adjusted normal breast tissues showed low expression of USP37, confirming that USP37 is overexpressed in human breast cancer samples." (PMID 34606619, 2021). "Moreover, a positive correlation between BLM and USP37 protein levels (P < 0.0001, R = 0.536) was observed in these breast carcinomas." (PMID 34606619, 2021). "Our data suggested that USP37 might be a therapeutic target agansist ADR resistance in breast cancer." (PMID 33390801, 2021). "In addition, USP37 is overexpressed in breast cancer samples and GEO database showed that high expression of USP37 is related to poor survival in breast cancers." (PMID 34606619, 2021). "In addition, GEO database showed that high expression of USP37 is significantly correlated with poor survival in breast cancer patients." (PMID 34606619, 2021). "USP37 expression in breast cancer samples was analyzed using the data collected from TCGA." (PMID 33390801, 2021). "Next, we further investigated USP37 as a potential target for breast cancer therapy in vivo." (PMID 34606619, 2021). "Moreover, clinical data from the GEO database indicated that increased expression of USP37 was markedly correlated with poor survival of breast cancer patients." (PMID 34606619, 2021).
breast carcinoma (continued). "Moreover, a positive correlation between BLM and USP37 protein levels was observed in the breast carcinomas." (PMID 34606619, 2021). "Additionally, the cycloheximide (CHX) chase assay was used to assess MCF-7 breast cancer cell line for the effect of USP37 upregulation on endogenous Gli-1 protein." (PMID 30482232, 2018). "USP37 expression was elevated in breast cancer tissues and breast cancer cell lines." (PMID 30482232, 2018). "Accumulation evidence has indicated that tumor cells undergoing EMT process are endowed with the trait of cancer stem-like cells, which further speculated USP37 as a CSC marker of breast cancer." (PMID 30482232, 2018). "Since USP37 was highly expressed in breast cancer stem cells, we further examined whether USP37 played a role in breast cancer stem cells behavior." (PMID 30482232, 2018). "Additionally, we used breast cancer cell lines to perform sphere-formation experiments and measured the differential expression of the USP37 gene." (PMID 30482232, 2018). "Additionally, USP37 knockdown enhanced the sensitivity of breast cancer cells to cisplatin in vitro and in vivo." (PMID 30482232, 2018). "Recent studies indicate that USP37 is a potential factor involved in breast cancer progression." (PMID 30482232, 2018). "Moreover, we found that knockdown of USP37 suppressed cell migration and invasion in breast cancer cells." (PMID 30482232, 2018). "Together, these data suggest endogenous USP37 may regulate Gli-1 protein stability in breast cancer." (PMID 30482232, 2018). "First, we observed an starkly different tendency within USP37 gene expression among different pathological subtypes of breast cancer cells, including the normal-like subtype having the lowest, and Luminal B type endowed with the highest expression levels of USP37 (p < 0.0001)." (PMID 30482232, 2018). "The expression of USP37 gene has been demonstrated to be elevated in patients with a recurrence of cancer, indicating that USP37 levels may be closely related to breast cancer distant metastasis." (PMID 30482232, 2018). "We detected that knockdown of USP37 in breast cancer cells could promote the sensitivity to cisplatin-induced cell death by the CCK-8 assay and colony formation assays." (PMID 30482232, 2018). "However, there was no direct evidence to identify the carcinogenic mechanism of the USP37 gene in breast cancer." (PMID 30482232, 2018). "Therefore, we concluded that USP37 gene plays a critical role in ADR resistance of breast cancer." (PMID 33390801, 2021). "In addition, we found that USP37 expression is up-regulated in breast cancer tissue arrays." (PMID 34606619, 2021). "In addition, USP37 is overexpressed in breast cancer samples, and is correlated with poor survival." (PMID 34606619, 2021). "Furthermore, USP37 knockdown sensitizes cancer cells to DNA-damaging agents in xenograft models, suggesting that the USP37–BLM axis may provide new therapeutic targets for overcoming chemo or radiotherapy resistance in breast cancer." (PMID 34606619, 2021). "Moreover, in vivo xenograft mouse model of breast cancer showed that tumors resulting from USP37 silenced cells are more sensitive to cisplatin, and have impaired HH target and stemness genes expression, together with lower proliferation ability compared to control group." (PMID 32531973, 2020). "Furthermore, upregulation of USP37 markedly promoted invasion and migration of breast cancer cells." (PMID 30482232, 2018). "We postulate that USP37 may represent a novel molecular target for breast cancer treatment." (PMID 30482232, 2018). "Therefore, USP37 levels could potentially serve as a specific oncogene involved in breast carcinoma progression." (PMID 30482232, 2018). "USP22 and USP36 regulate the cellular turnover of c-MYC in breast cancer, and c-MYC expression is stabilized by USP28 and USP37 in colon carcinoma and lung cancer, respectively." (PMID 39664521, 2024).